FLT3 (fms related receptor tyrosine kinase 3)
Diseases named in the same sentence as FLT3 in open-access papers (continued):
Sharing a sentence is not in itself a finding about the gene and the disease.
myeloid neoplasm (39 papers, 2009 to 2025). Proliferation of myeloid cells originating from a primitive stem cell. "FMS-like tyrosine kinase 3 (FLT3) genetic variants are commonly seen in high-grade myeloid neoplasms and are typically gain-of-function mutations associated with a proliferative disease phenotype." (PMID 39773519, 2025). "Several FLT3 inhibitors, for example, lestaurtinib and sorafenib, have been developed and investigated in human myeloid neoplasm patients with FLT3-ITD mutations." (PMID 36072760, 2022). "At the same time, SF3B1 (Splicing Factor 3b Subunit 1), U2AF1 (U2 Small Nuclear RNA Auxiliary Factor 1), NPM1, and FLT3 are rarely mutated in GATA2-mutated myeloid neoplasms." (PMID 35054439, 2021). "FLT3 (FMS-related tyrosine kinase 3) acts as an oncogene in myeloid neoplasms which is associated with several signal transduction pathways." (PMID 34194582, 2021). "The oncogenic role of FLT3 in myeloid neoplasms usually results from activating somatic mutations including length mutation (LM)/internal tandem duplication (ITD) in the juxtamembrane domain and point mutations within the tyrosine kinase domain (TKD)." (PMID 34194582, 2021). "Genetic aberration of FLT3 mutation has a high frequency of onset in myeloid neoplasm." (PMID 34194582, 2021). "Our findings suggest that, besides the oncogenic activation of FLT3-ITD/TKD mutations observed in myeloid neoplasm, amplification involving FLT3 may be another mechanism contributing to leukemogenesis." (PMID 34194582, 2021). "Studies have validated that both FLT3-ITD and FLT3D835Y are driver mutations in AML that cause myeloid neoplasms in murine models, FLT3-ITD occurs in about 25% of AML patients and represents an unfavorable prognosis unless nucleophosmin 1 (NPM1) mutations are present." (PMID 32817792, 2020). "Moreover, recent knock-in models of BCR-ABL and FLT3-ITD (a third tyrosine kinase associated with myeloid malignancies) have both been shown to compromise HSC self-renewal in transplantation experiments." (PMID 23750118, 2013). "The co-occurrence of U2AF1 and signaling gene mutations also differed across myeloid neoplasms, with NRAS and FLT3 mutations being more common with S34 mutations and CBL, PTPN11 and CSF3R mutations more common with R156/Q157 mutations." (PMID 40386435, 2025). "Myeloid neoplasms are known to have chromosomal translocations that regulate PML-RARA, CBFB-MYH11, and RUNX1-RUNX1T1 myeloid transcription factors and JAK2, FLT3, KIT, and RAS, activating driver mutations in signaling pathways." (PMID 38392574, 2024). "ASXL1mt in myeloid neoplasms were considered to be ubiquitously accompanied by mutations of RUNX1, SRSF2, STAG2, NRAS, or IDH2, in addition to wild‐type NPM1 and FLT3,14, 21, 22, 28 which was aligned with the mutation profile in our cohort." (PMID 38146893, 2023). "In this regard, our data are of interest as they further validate FLT3 as target antigen for myeloid malignancies." (PMID 37587502, 2023). "Additional clinical trials will be required to explore this field, with the hope that FLT3 inhibitors will play a positive role along with the conventional chemotherapies for the treatment of myeloid neoplasm." (PMID 34194582, 2021). "Other genes commonly mutated in myeloid neoplasms, such as FLT3 (fms like tyrosine kinase 3), DNMT3A (DNA Methyltransferase 3 Alpha), IDH1/2 (Isocitrate Dehydrogenase (NADP(+)) 1/2), NPM1 (Nucleophosmin 1), and RUNX1, are rare and almost mutually exclusive." (PMID 35054439, 2021). "Other co-mutations often seen in myeloid neoplasms with germline RUNX1 are in DNMT3A, FLT3, GATA2, PHF6 (PHD finger protein 6), BCOR (BCL6 Corepressor), WT1, and TET2." (PMID 35054439, 2021).
myeloid neoplasm (continued). "Since the current case is supposed to be the first to describe the amplification of FLT3 in myeloid neoplasms, it is hard to tell the further mechanism among these oncogenes." (PMID 34194582, 2021). "In order to further prove a potential role for FOXM1 in AML chemoresistance, we induced an FLT3-ITD–driven myeloid neoplasm in a FOXM1-overexpressing transgenic mouse model and demonstrated significantly higher residual disease after standard chemotherapy." (PMID 30089730, 2018). "Indeed, at least one pathogenic mutation (WT1, FLT3-ITD, IDH2 or PTPN11 mutation) has been identified in all the reported myeloid tumors harboring NPM1::MLF1." (PMID 39443736, 2024). "This change resulted in an increase in the diagnosis of certain subtypes (such as AML with NPM1 and FLT3-ITD mutations), while other subtypes (such as AML with bone marrow proliferative abnormalities and treatment-related myeloid neoplasms) gained new recognition." (PMID 37193689, 2023). "Current research results indicate that FLT3-ITD may lead to unfavourable impact on the prognosis especially a high relapse rate in patients with myeloid neoplasm, while the impact of FLT3-TKD on the prognosis is still unclear." (PMID 34194582, 2021). "The vast majority of wild type mice have normal bone marrow, the majority of Flt3+/ITD mice develop a myeloid neoplasm (primarily MPN), the predominant phenotype in the Wt1+/R394W mice evaluated is MDS, and the majority of Flt3+/ITD/Wt1+/R394W mice develop an MDS/MPN." (PMID 30450160, 2018). "Interestingly, genes commonly mutated in AML and other myeloid neoplasms, such as FLT3, NPM1, KIT, RUNX1, and DNMT3A, were absent in our cohort." (PMID 40526100, 2025). "Several zebrafish models associated with myeloid malignancies have been previously reported, including transgenic zebrafish that exhibit K-RASG12D, NUP98-HOXA9, Stat5 (H298R), Stat5 (N714F), NPM1, tel-jak2a, AML1-ETO, FLt3-ITD, FLT3-TKD (D835Y), MYCN, or MOZ/TIF2 expression." (PMID 26064935, 2015).
chronic myeloid leukemia (35 papers, 2012 to 2026). "Insights from studies on chronic myeloid leukemia (CML) have helped in the development of next-generation FLT3 inhibitors to improve treatment outcomes in AML patients." (PMID 39757310, 2025). "We incubated MV4-11 cells, MOLM-13 cells, RS4-11 cells, and K562 cells (from a 53-year-old woman with chronic myeloid leukemia, FLT3 null) with 2 nM AC220 and 1 μM RGFP966 for 24 h." (PMID 34665271, 2022). "GRB10 interacts with oncogenic Bcr-Abl in chronic myelogenous leukemia, and with active Raf-1 to promote cell survival, and it also binds with FLT3 to enhance AML cell proliferation, which is suggestive of oncogenicity." (PMID 27977763, 2016). "The combination of an inhibitor of HDAC and 17-AAG is highly active in vitro against cells from chronic myeloid leukemia in blast crisis and AML cells harboring a FLT-3 mutation." (PMID 23047954, 2012). "We speculate that hyperactive kinases, such as FLT3-ITD in AML cells or BCR-ABL in chronic myeloid leukemia cells and a subset of ALL cells, activate MYC and POLD1, and that this attenuates the cytotoxic effects of HDAC10 inhibition." (PMID 40301616, 2025). "DNMT3A mutation happened in a variety of cancers such as colorectal cancer, lung cancer, chronic myelocytic leukemia, but is mainly with AML and usually occur with other types of mutations, such as FLT3, NPM1, C/EBP alpha, resulting in synergistic effects in AML." (PMID 36303144, 2022). "Given that K562 was derived from chronic myeloid leukemia patient, the Bcr/Abl1 translocation present in the genetic background potentially could alter the biology of Flt3 in our findings." (PMID 33363015, 2020). "Development of more potent TKIs, such as the broad-spectrum ponatinib, active against resistant mutations of FLT3 and BCR-ABL1 in acute and chronic myeloid leukemia, respectively, may be of future clinical benefit in FGFR1 MPN." (PMID 23082258, 2012). "Imatinib, a first line chemotherapeutic treatment for chronic myeloid leukemia, is a selective tyrosine kinase inhibitor of PDGF signaling, among other pathways including FLT3, Lck and MAPK cascades." (PMID 33800271, 2021). "GSEA showed that gene sets of AML with FLT3-ITD, HSC (hematopoietic stem cell)/LSC and CML (chronic myelocytic leukemia) quiescence were enriched in both SH3TC2-DT and SH3TC2 high-expression phenotype." (PMID 32637351, 2020). "Similar findings have been reported for FMS related receptor tyrosine kinase (FLT3) internal tandem duplication (ITD) leukemia and BCR-ABL driven chronic myeloid leukemia (CML)." (PMID 32645016, 2020). "Wild-type FLT3 is overexpressed in most cases of B-lymphoblastic leukemia and AML and in a smaller percentage of T-lineage ALL and chronic myeloid leukemia (CML) in blast crisis." (PMID 29209600, 2017). "A previous study has shown that ponatinib, which is the inhibitor of BCR-ABL and fms-like tyrosine kinase 3 (FLT3), is a substrate of P-gp and can reduce the amounts of ABCB1 mRNA in human chronic myelogenous leukemia cell line." (PMID 29061940, 2015). "FLT3 is expressed in most chronic myeloid leukemia (CML) blast crisis patient samples, irrespective of phenotype, as well as in several chronic lymphocytic leukemia (CLL) samples." (PMID 25295230, 2014).
breast carcinoma (29 papers, 2007 to 2025). "We observed a strong association of high FLT3 expression with immune cell infiltration, which was also observed in the cervical and breast cancer studies." (PMID 38327131, 2024). "Few have the studies evaluated Fms-like TyrosineKinase-3 (FLT3) in prognostic risk, immunotherapy or any other treatment of breast cancer." (PMID 36159964, 2022). "The median AUC of the BRCA1 mutant type cancer cell lines was smaller than that of the wild-type, indicating that an FLT3 inhibitor (sunitinib) has potential therapeutic effects for hereditary breast cancer and ovarian cancer with a BRCA1 mutation." (PMID 33627666, 2021). "Recently, a series of studies linked AXL to several receptor tyrosine kinase inhibitors including EGFR inhibitors in lung cancer, head and neck cancer and colorectal cancer, HER2 inhibitors in breast cancer, and FLT3 inhibitors in AML." (PMID 36835239, 2023). "It has been reported that midostaurin triggers G2/M arrest in breast cancer cell lines through inhibition of the AURK family proteins, which supports the notion of an association of AURK suppression and G2/M arrest in FLT3-WT AML." (PMID 36865133, 2023). "Based on these results and cross referencing with the literature, we determined PIK3R1, a reported target in breast cancer, acts as a direct target of miR-155 in FLT3-ITD+AML." (PMID 36605494, 2023). "Patients and methods: Based on transcriptome and methylation data mined from The Cancer Gene Atlas (TCGA), we explored the clinical features of FLT3 expression in 1079 breast cancer samples." (PMID 36159964, 2022). "Genomic amplification of FLT3 has been reported in solid tumors including colorectal cancer, breast cancer, and gastric cancer." (PMID 34194582, 2021). "In the TCGA data set, FLT3 amplification can be found in various solid tumors such as colon cancer, stomach cancer, prostate cancer, and breast cancer." (PMID 34194582, 2021). "In the TCGA data set, the incidence of FLT3 amplification was highest in colorectal cancer (34.6%), breast cancer (10.5%), and gastric cancer (8.3%) in the order of frequency in all FLT3-amplified cancer." (PMID 27906677, 2017). "Here, we employed only breast cancer cell lines, in which the effect against FLT-3 was excluded from the analysis, and picked up Aurora kinases as the candidate for the target of midostaurin in TNBC cells." (PMID 26141684, 2015). "Despite its seemingly low frequency, FLT3 amplification shouldn’t be overlooked, especially considering its broader presence in other solid tumors such as gastric cancers, lung adenocarcinomas, and breast cancers." (PMID 39011472, 2024). "FLT3 mutations are not common in any sub-type of breast cancer and among sub-types, FLT3 expression is lowest in TNBC." (PMID 38001268, 2024). "Our study focused on investigating the function of FLT3 in breast cancer." (PMID 36159964, 2022). "Radiation in combination with immunostimulatory molecules such as Interleukin-2 (IL2), Toll-like receptor (TL-R) ligands and FMS-like tyrosine-kinase 3 (Flt-3) ligand have been used pre-clinically to engender the abscopal effect in mouse models of breast cancer." (PMID 29644338, 2018). "The results indicated that EMC2, G6PD, FLT3, IFNG, ANO6, and SLC1A4 were positively correlated with ferroptosis while CISD1, TP63, and BRD4 were negatively correlated with ferroptosis in breast cancer." (PMID 34222241, 2021). "The breast cancer cells do not express FLT-3, and thus it is of interest to identify the target of midostaurin in the TNBC cell lines." (PMID 26141684, 2015). "Previously, we reported that the E3 ubiquitin ligase SIAH2 promotes the proteasomal degradation of the mutant receptor tyrosine kinase (TK) FLT3-ITD in leukemic cells and of the non-receptor TK ACK1 in breast cancer cells." (PMID 24833526, 2014).
breast carcinoma (continued). "The role of necroptosis-related genes in breast cancer, such as FASLG, FLT3, HSPA4, IDH2, IPMK, LEF1, and SLC39A7, has not been extensively studied, and these necroptosis-related genes have been confirmed to regulate the biological processes of necroptosis in various types of tumors." (PMID 36675706, 2022).
lung cancer (26 papers, 2013 to 2025). A malignant neoplasm involving the lung. "Here, we found that FLT3 was linked to an improved survival, whereas its expression was elevated in the lung cancer samples." (PMID 39311766, 2024). "FLT3 harbors germline mutations that appear to be present in the majority of lung cancer patients analyzed in this study." (PMID 35330454, 2022). "Other frequently mutated genes in the tumor tissue samples used in our lung cancer study were FLT3 (altered in 87% of the samples), KDR (84%), CSF1R (72%), PIK3CA (59%), and ERBB4 (53%)." (PMID 35330454, 2022). "High expression of FMS‐related tyrosine kinase 3 (FLT3) in the non‐small cell lung cancer tumor microenvironment significantly boosts immune cell infiltration, especially by natural killer cells and dendritic cells." (PMID 38327131, 2024). "These GO terms encompass six genes relevant to lung cancer found primarily in “Pathways in cancer” GO and partially overlapping with two other GOs: FLT3, FOXO1, CSF1R, RUNX1, PPARG, and TGFBR2." (PMID 39201328, 2024). "FGF2-mediated activation of FGFR1 promotes resistance to EGFR inhibitors in lung cancer, FLT3 inhibitors in AML, and KIT inhibitors in gastrointestinal stromal tumors." (PMID 37598282, 2023). "In this study, we identified that gilteritinib has an inhibitory effect on lung cancer cells (LCCs) without FLT3 mutation in vitro and in vivo." (PMID 39349433, 2024). "Immune cell infiltration (especially cytotoxic CD8+ lymphocytes) is a recognized prognostic factor in lung cancer, which may partially explain the beneficial effect of FLT3 expression on DFS." (PMID 38327131, 2024). "In similar with gilteritinib, quizartinib improved the anti-cancer effect of abemaciclib in lung cancer cells, indicating that FLT3 might confer synthetic lethality to CDK4/6 inhibition." (PMID 35814226, 2022). "To identify potential drugs that might sensitize abemaciclib, we employed FDA-approved small-molecule protein kinase inhibitors to co-treat with abemaciclib in lung cancer cells, and found that mTOR inhibitor, rapamycin and FLT3 inhibitor, gilteritinib enhanced the cytotoxicity of abemaciclib." (PMID 35814226, 2022). "In addition, quizartinib is an another selective FLT3 (target of gilteritinib) inhibitor that is also effective to combine with abemaciclib to inhibit proliferation of lung cancer cells, suggesting that FLT3 might confer synthetic lethality to CDK4/6 inhibition." (PMID 35814226, 2022). "In addition, based on prior clinical experience using other inhibitors in lung cancer (e.g., switching crizotinib to alectinib or gefitinib to osimertinib), AML cells will almost certainly acquire further resistance to the next-generation FLT3 inhibitors through additional mutations." (PMID 30344940, 2018). "Similar efforts to identify candidate biomarkers from phosphoproteomics analyses have recently been presented for dasatinib in nonsmall-cell lung cancer, for PI3K pathway inhibitors, and for the FLT3-inhibitor quizartinib in AML." (PMID 28450419, 2017). "The role of FLT3 in lung cancer is not clear now, while FLT3 ligands were considered as hematopoietic stimulators and can be employed in lung immune cell populations." (PMID 39311766, 2024). "Toceranib phosphate is also capable of blocking PDGFR, VEGFR, Flt-3, CSF1R, RET, ALK, and AXL, which may provide potential benefits for dogs with primary lung cancer." (PMID 39902337, 2024). "Class III receptor tyrosine kinase (RTK) inhibitors targeting mainly FLT3 or c-KIT have not been well studied in lung cancer." (PMID 31554189, 2019).
lung cancer (continued). "As a class III/V multikinase inhibitor, Sunitinib was reported to suppress various kinds of tumors, such as human metastatic renal cell carcinoma, lung carcinoma, glioblastoma, melanoma by inhibiting the activation of VEGFR-1, 2 and 3, PDGFR-α, β, Kit, Flt3 and RET." (PMID 29152075, 2017).
melanoma (22 papers, 2007 to 2025). A malignant, usually aggressive tumor composed of atypical, neoplastic melanocytes. "A phase II trial (NCT02129075) showed that poly-ICLC and fms-like tyrosine kinase 3 (Flt3) ligand pre-treatment enhanced responses to dendritic cell (DC)-targeting vaccines in melanoma patients." (PMID 37492581, 2023). "Recently, a phase II trial (NCT02129075) showed that fms-like tyrosine kinase 3 (Flt3) ligand pre-treatment enhanced responses to dendritic cell (DC)-targeting vaccines in melanoma patients." (PMID 36275666, 2022). "A study demonstrated the optimization of intranodally administrated RNA vaccine in melanoma-bearing mice by systematically co-administrating DC-activating Fms-like tyrosine kinase 3 (FLT3) ligand, which is an adjuvant." (PMID 33593376, 2021). "In case of B16-FLT 3, murine B16 melanoma cells where transfected with the gene for the Flt3-L cytokine (FLT3-Fvax), which also has the role of promoting the rejection of established murine melanomas." (PMID 23890195, 2013). "Genes where a statistically significant difference in mutation rate was observed were APC (p = 9 × 10−7) in CRC, STK11 (p = 0.008) in NSCLC, and CDKN2A (p = 0.02), ERBB4 (p = 9 × 10−4), FLT3 (p = 0.02), and KDR (p = 0.01) in melanoma." (PMID 28196074, 2017). "Although Sorafenib has shown little promise as a single agent in melanoma patients, Sorafenib targets multiple kinases including VEGFR, PDGFR, FLT3, C-Kit and the RAF family." (PMID 27152946, 2016).